FOXP3 (forkhead box P3)
Diseases named in the same sentence as FOXP3 in open-access papers (continued):
Sharing a sentence is not in itself a finding about the gene and the disease.
autoimmune disease (continued). "In the case of Tip60, these compounds reduce the process of histone acetylation and induce association with the Foxp3 protein which has been used to treat autoimmune diseases (mainly colitis and collagen-induced arthritis)." (PMID 35207219, 2022). "The mutation or genetic deletion of Foxp3 caused a severe autoimmune disease known as IPEX syndrome." (PMID 35948909, 2022). "Deficiency of Treg cells caused by mutations of Foxp3 results in early onset autoimmune disease as demonstrated in Foxp3 mutant scurfy mice and humans with IPEX (immune dysregulation, polyendocrinopathy, enteropathy, X-linked) syndrome." (PMID 35418975, 2022). "Loss of Foxp3 expression or function can lead to the development of autoimmune diseases, while ex vivo generated iTregs from Foxp3-negative CD4+ Teff cells exhibit the suppressive and phenotypic characteristics like nTreg." (PMID 36500570, 2022). "The transcription factor forkhead box P3 (Foxp3) was also identified as a marker for Tregs, and mutation or deficiency in Foxp3 can lead to a fatal multi-organ autoimmune disease." (PMID 34067829, 2021). "Treg is a subset of CD4+ T cells which are characterized by the expression of transcription factor Foxp3 and helps to keep inflammation under control and lower the autoimmune disease risk in healthy individuals." (PMID 34305913, 2021). "Mutations in the master regulator FOXP3 and related components have been linked to autoimmune diseases in humans, such as IPEX, and a scurfy-like phenotype in mice." (PMID 34675933, 2021). "It is worthy of note as well that FoxP3 was found to be an important player in the suppressive function of Treg cells, and its loss or mutation leads to the development of autoimmune diseases." (PMID 33672515, 2021). "The transcription factor FOX head P3 (FoxP3) is a major regulator of the development and function of Tregs, in which mutation of the FoxP3 gene results in severe autoimmune disease." (PMID 34479568, 2021). "The nuclear transcription factor forkhead box protein 3 (FoxP3) has been found to be essential for the regulation of Treg-cells and mutations of FoxP3 have been linked to several autoimmune diseases." (PMID 34064075, 2021). "Several studies on Treg in other autoimmune diseases, such as type 1 diabetes and rheumatoid arthritis, suggest a loss of Foxp3 expression and the generation of pathogenic Th17 cells, in association with Foxp3 instability in Tregs in these diseases." (PMID 34220827, 2021). "Recently, a crucial role of the X-Linked Forkhead Box P3 (FoxP3) for the development and the stability of Tregs has emerged, and FOXP3 gene polymorphisms have been associated with the susceptibility to autoimmune diseases." (PMID 33806248, 2021). "This idea is supported by the fact that loss of function mutations in FOXP3 causes autoimmune diseases affecting multiple organs, called IPEX syndrome." (PMID 33665689, 2021). "Many polymorphisms in the gene codifying for Foxp3 have been associated with reduced levels of Foxp3 and impaired suppressive function of Treg cells, resulting in the development of autoimmune diseases." (PMID 33806248, 2021). "FOXP3 plays an essential role in counterbalancing the overactive immune system, and its deficiency is linked to autoimmune diseases and ASD." (PMID 33562037, 2021). "An association between single nucleotide polymorphisms (SNPs) of the FOXP3 gene and autoimmune diseases, such as allergy, Graves’ disease, and systemic lupus erythematosus, has been described." (PMID 33806248, 2021). "Although the influence of FOXP3 SNPs on disease risk has been established in several autoimmune diseases, such as systemic sclerosis and asthma, contrasting results have been reported in MS patients." (PMID 33806248, 2021). "In patients FoxP3 mutation and Treg deficiency results in an autoimmune disease known as IPEX, immunodysregulation polyendocrinopathy enteropathy, X-linked." (PMID 34575843, 2021).
autoimmune disease (continued). "Foxp3 controls the expression of IL-2, CD25 (IL-2 receptor α-chain), CD122 (IL- 2 receptor β-chain), and CTLA-4, and deficiency in any of them results in autoimmune diseases observed in Foxp3 deficiency." (PMID 33717139, 2021). "Like in the case of Foxp3 and Ctla4, many DRs are found in SEs in the Il2ra gene, in which autoimmune-disease-associated SNPs (e.g., T1D and MS) are located." (PMID 34281195, 2021). "Downregulated Foxp3 expression commonly causes immune dysregulation, which elicits autoimmune diseases." (PMID 33329608, 2020). "Canonical Tregs express the transcription factor FoxP3, and their importance in maintaining self-tolerance is illustrated by Foxp3 mutation which results in fatal multi-organ autoimmune disease in both mice (scurfy mice) and humans (IPEX syndrome)." (PMID 32966314, 2020). "So, understanding the molecular relationship between Foxp3 and autoimmune diseases can help us for the treatment of Treg-associated autoimmune diseases." (PMID 33519807, 2020). "Mutations of the single X-chromosomal FOXP3 gene in male individuals cause the inherited autoimmune disease immune dysregulation, polyendocrinopathy, enteropathy, and X-linked (IPEX) syndrome." (PMID 33194927, 2020). "Since Treg cells are essential for the maintenance of immunological tolerance and Foxp3 is the master transcription factor for Treg cells, mutations in the Foxp3 gene in mice or in the FOXP3 gene in humans lead to severe autoimmune diseases and death." (PMID 33126494, 2020). "Functional deficits in CD4+ CD25+ FOXP3+ Treg cells after fludarabine treatment are one of the risk factors for autoimmune diseases in CLL patients." (PMID 33004832, 2020). "Treg dysfunction in autoimmune diseases can be grouped according to different factors: i) Genetic disease like germline mutations in the Foxp3 locus." (PMID 33584708, 2020). "Taken together, these findings underline the key relevance of Foxp3 in the control of Treg cell function and how its related defects concur to autoimmune disease pathogenesis and progression." (PMID 32117202, 2019). "Defective or down-regulated Foxp3 has been shown to contribute to the loss of Treg cell function and the concomitant development of autoimmune disease." (PMID 30974919, 2019). "Another study addressed the role of Batf in Treg biology, by generating strains of mice carrying specific mutant FOXP3 alleles, that were previously identified in human patients with autoimmune disease driven by globally compromising Treg cell physiology." (PMID 31340499, 2019). "L. reuteri prolongs the survival of mice suffering from Foxp3+ Treg-deficiency-induced autoimmune disease (called the scurfy mouse)." (PMID 30899262, 2019). "In patients with autoimmune diseases, abnormality of Foxp3 expression resulted in IRF4-deficiency, which caused incapable of starting the transcription of downstream gene and impaired immunosuppressive function of Treg cells." (PMID 31380412, 2019). "Impaired acetylation of Foxp3 has been associated with the pathogenesis of several autoimmune diseases, such as rheumatoid arthritis (RA) and Hashimoto's Thyroiditis (HT)." (PMID 32117202, 2019). "Depletion of CD4+CD25+FOXP3+ Treg cells by a variety of methods is also able to cause similar autoimmune diseases in otherwise normal rodents." (PMID 31340499, 2019). "The mutations of the FOXP3 gene disturb the function of Tregs, therefore resulting in the development of various autoimmune diseases." (PMID 31772947, 2019). "The key evidence of Forkhead box-p3 (Foxp3) as regulatory T (Treg) cell lineage-specific transcription factor is that its gene mutations lead to autoimmune disease in both mice and humans." (PMID 32117202, 2019). "FOXP1 is in the same Foxp subfamily as FOXP3; these genes encode for a family of transcription factors recognized for its involvement in autoimmune disease, speech and language disorders, and lung development." (PMID 31324826, 2019).
autoimmune disease (continued). "Immune dysregulation, polyendocrinopathy, enteropathy, X-linked (IPEX) syndrome is an autoimmune disease caused by mutations in the forkhead box protein 3 gene (FOXP3), which encodes a key regulator of immune tolerance." (PMID 30385752, 2018). "Tregs express the transcription factor forkhead box P3 (FOXP3), which is very important for Tregs development and function, since defects in the FOXP3 gene cause a human lethal autoimmune disease." (PMID 29719821, 2018). "FOXP3 is necessary to generate the full Treg signature and functionality, and mutations in FOXP3 lead to severe lethal autoimmune disease in scurfy mice and men." (PMID 29730990, 2018). "TH17 cells originating from regulatory T (Treg) cells upon loss of the Treg-specific transcription factor Foxp3 accumulate in sites of inflammation and aggravate autoimmune diseases." (PMID 30413714, 2018). "The FOXP3 –2383C>T (rs3761549) polymorphism is located in the first intron, close to the FOXP3 promoter region, and has been associated with susceptibility to autoimmune diseases." (PMID 30021560, 2018). "FOXP3 variants are associated with susceptibility to autoimmune diseases and infections, but the underlying mechanisms are poorly understood." (PMID 30487748, 2018). "Mice that lack FoxO1 in Treg cells (FoxP3-cre FoxO1fl/fl) mice exhibit severe autoimmune disease that is reminiscent of the disease found in FoxP3-deficient scurfy mice." (PMID 28267764, 2017). "FOXP3 is considered as master regulator of Treg development and function, and its deletions or mutations are associated with severe, even lethal autoimmune diseases." (PMID 27730344, 2017). "It was found that the number of CD4+CD25+Treg cells decreased in the Foxp3 gene knockout or mutation mice, greatly increasing the incidence of autoimmune diseases." (PMID 29156761, 2017). "Currently, 90 SNPs have been identified in the FOXP3 gene region, and several have been identified as risk factors for a number of malignant and autoimmune diseases." (PMID 28421078, 2017). "Here the authors show that Lkb1 also maintains Foxp3 expression and suppressive function in regulatory T (Treg) cells, and that Treg-specific Lkb1-deficient mice develop fatal autoimmune disease." (PMID 28621313, 2017). "Foxp3 gene polymorphisms were associated with various autoimmune diseases and clearance of viral infections." (PMID 28298239, 2017). "In the mouse model, Foxp3-deficient scurfy (SF) mice develop a lethal autoimmune disease which closely resembles the IPEX syndrome." (PMID 29270168, 2017). "On the one hand, the rs3761548 is an intronic FOXP3 polymorphism shown to be associated with autoimmune disease susceptibility and reduced transcription of the FOXP3 gene." (PMID 27834806, 2016). "Foxp3 was identified as a lineage-defining transcription factor (TF) for Tregs in mice and humans, and loss of Foxp3 leads to severe lethal autoimmune disease in mice and men." (PMID 26886923, 2016). "In vivo, loss of FOXP3 has also been documented in the setting of autoimmune disease fetal acute infections, TLR stimulation, and homeostatic proliferation." (PMID 26379673, 2015). "Specifically, they displayed loss of CD4+FoxP3+ Treg cell suppressive function, hyperactivation of effector T cells, lymphocyte infiltration of multiple target organs, and fatal autoimmune disease." (PMID 25852682, 2015). "Here, we discuss the cellular and molecular mechanisms underlying FOXP3-mediated regulation of Treg cells and also the possible effect that gender difference has on Treg cells and autoimmune diseases." (PMID 26441996, 2015). "Regulatory T cells (Tregs) expressing FOXP3 are essential for the maintenance of self-tolerance and are deficient in many common autoimmune diseases." (PMID 25457307, 2015).
autoimmune disease (continued). "The significance of FOXP3 gene was identified by its mutations that cause fatal autoimmune diseases in early life, which is now termed immunodysregulation, polyendocrinopathy, enteropathy, and X-linked (IPEX) syndrome in mice and humans." (PMID 26623425, 2015). "Mutations in their lineage-defining transcription factor forkhead box P3 (Foxp3) cause severe autoimmune disease in human and mouse." (PMID 25978037, 2015). "Consistently, IPEX patients, who suffer from a devastating autoimmune disease, were found to have mutations in the Foxp3 gene." (PMID 25566245, 2014). "tTregs, expressing high levels of IL-2 receptor alpha chain (CD25), and the transcription factor Foxp3, are the most important, since mutations or deletions in these genes cause fatal autoimmune diseases in both mice and men." (PMID 23818888, 2013). "IL-23 induces differentiation of IL-17-producing CD4+ helper T cells (TH17) and CD4+CD25+Foxp3+ regulatory T cells (Tregs) that favor the development of chronic infection and autoimmune diseases under pathogenic conditions." (PMID 23967307, 2013). "This affection is characterized by splenomegaly, insulitis, hepatomegaly, lymphadenopathy, and massive lymphocytic infiltrates in the skin and liver, suggesting that mutation in FOXP3 leads to an autoimmune disease." (PMID 24350059, 2013). "The deficiency of Treg function (e.g., owing to forkhead box P3, Foxp3, gene mutation) would evoke various autoimmune diseases, immunopathology, and allergy." (PMID 24288462, 2013). "Loss or reduced function of FoxP3 leads to severe immunological disorders characterized by lymphocyte hyperproliferation, organ infiltration and autoimmune disease, both in man and mouse." (PMID 23593464, 2013). "On one hand, mutation or deletion of the gene encoding Foxp3 causes severe autoimmune diseases in both human and mice, due to a malfunction of Tregs." (PMID 23578365, 2013). "Dicer deficiency in Foxp3+ cells leads to the development of fatal autoimmune diseases resembling the Foxp3 knockout phenotype." (PMID 23386861, 2013). "Spontaneous autoimmune disease in Tg4 mice is controlled by functional FoxP3+ Treg cells, as Rag-deficient Tg4 mice, which are naturally devoid of Treg cells, develop encephalomyelitis at 11–12 weeks of age." (PMID 23593464, 2013). "Several previous studies have found an association between Foxp3 gene polymorphisms and autoimmune diseases, such as systemic lupus erythematosus (SLE), autoimmune thyroid diseases (AITDs), type I diabetes (TID), and allergic rhinitis." (PMID 23560055, 2013). "FoxP3 deficiency in humans leads to a severe autoimmune disease named IPEX and represented by immune dysregulation, polyendocrinopathy, enteropathy, and X-linked syndrome that occur early in infancy." (PMID 23133752, 2012). "Epigenetic changes have been shown to affect FOXP3 and IFNγ expression and mutations and/or deficiencies in FOXP3 or IFNγ can result in development in autoimmune disease, infections or asthma." (PMID 23226205, 2012). "Established markers of Treg functionality are lacking, however polymorphisms in Tregs effector genes such as CTLA-4, GITR, FoxP3 have been linked to susceptibility to autoimmune diseases in humans, including MS." (PMID 21731726, 2011). "Approximately 10% of CD4 T cells express the transcription factor FoxP3 (forhead box P3 transcription factor); humans and mice with inactivating Foxp3 mutations have autoimmune diseases." (PMID 22112546, 2011). "Forkhead box p3 (FoxP3)-expressing regulatory T cells (Tregs) have been clearly implicated in the control of autoimmune disease in murine models." (PMID 20384988, 2010). "Mutations in exon 7 have been linked to IPEX, a severe autoimmune disease suggested to be caused by impaired dimerization of the FOXP3 protein." (PMID 19568423, 2009). "Specific deficiency of Ctla4-/- in natural Foxp3+CD4+ regulatory T cells results in spontaneous autoimmune disease." (PMID 19951419, 2009).
autoimmune disease (continued). "FOXP3 overexpression is one strategy to mitigate the risk of Treg instability, as Tregs exposed to proinflammatory conditions can lose FOXP3 expression and adopt a proinflammatory phenotype, potentially exacerbating autoimmune disease." (PMID 40589763, 2025). "However, deletion of the enzyme transketolase (TKT) in mice induces impaired Treg suppressive function, despite normal FoxP3 expression levels and leads to unhampered oxidative phosphorylation causing fatal autoimmune disease." (PMID 40963621, 2025). "In several autoimmune diseases, nTreg instability and plasticity may be due to epigenetic modifications and mutations of the FoxP3 gene (see Section 4)." (PMID 39000278, 2024). "Changes in FOXP3 splice variant expression has been studied in autoimmune diseases." (PMID 38660296, 2024). "Few studies have investigated FOXP3 polymorphisms in conditions other than autoimmune diseases.One study proposed that the immunomodulatory effects on individuals with viral hepatitis are influenced by FOXP3 SNPs, specifically, rs2232365, rs3761549, and rs3761548." (PMID 39117877, 2024). "The importance of FOXP3 in immunoregulation is highlighted by the significant associations between inactivating FOXP3 mutations and increased susceptibility to autoimmune diseases such as the IPEX (immunodysregulation, polyendocrinopathy, enteropathy, X-linked) syndrome." (PMID 37895245, 2023). "The FoxP3 protein is the master regulator for development and function of CD4+CD25+CD127low Treg cells, where mutations of FoxP3 gene impair their development and function that may result in severe autoimmune disease." (PMID 37736101, 2023). "Notably, Foxp3 gene polymorphisms are also candidate risk factors in autoimmune diseases, including CITP." (PMID 37628621, 2023). "Polymorphisms in FoxP3 may change its expression level and weaken the inhibitory function of Tregs, thus affecting the role of Tregs in the immune response and potential autoimmune diseases." (PMID 37904681, 2023). "The loss of function of Foxp3 leads to autoimmune disease in both animals and humans." (PMID 37197653, 2023). "Furthermore, different SNVs in the promoter region of FOXP3 have been associated with the susceptibility and prognosis of autoimmune diseases, such as multiple sclerosis, rheumatoid arthritis, psoriasis, and systemic sclerosis." (PMID 35905575, 2022). "FOXP3-expressing Tregs are important for the maintenance of peripheral tolerance and perturbations in the development of Tregs is known to be associated with autoimmune diseases such as MS." (PMID 35928722, 2022). "Previous studies demonstrated that variations in FOXP3 may cause immune response impairment and contribute to X-linked autoimmune disease development." (PMID 35905575, 2022). "However, strategies targeting FOXP3 bear the risk for the development of autoimmune disease as FOXP3 expression is most likely not limited to tumor tissues." (PMID 36405718, 2022). "Defective Foxp3 expression involving abnormal Treg development and function may predispose patients to several autoimmune diseases." (PMID 35935991, 2022). "CD4+CD25+ regulatory T (Treg) cells that express the transcription factor forkhead box protein 3 (Foxp3) are critical for maintaining immune homeostasis and preventing autoimmune disease and tissue damage caused by excessive or unnecessary immune activation, including autoimmune kidney diseases." (PMID 35251009, 2022). "Foxp3 loss-of-function or induced ablation of Treg cells results in a fatal autoimmune disease featuring all known types of inflammatory responses with every manifestation stemming from Treg cell paucity, highlighting a vital function of Treg cells in preventing fatal autoimmune inflammation." (PMID 34426690, 2021).